PIAS1 (protein inhibitor of activated STAT 1)
Diseases named in the same sentence as PIAS1 in open-access papers (continued):
Sharing a sentence is not in itself a finding about the gene and the disease.
osteosarcoma (1 paper, 2021). A usually aggressive malignant bone-forming mesenchymal neoplasm, predominantly affecting adolescents and young adults. "The proapoptotic function of PIAS1 was initially demonstrated in human 293T cells and human osteosarcoma U2OS cells." (PMID 34195189, 2021).
prediabetes (1 paper, 2019). "A previous study has shown that PIAS1 is downregulated in white adipose tissue of mice with prediabetes, whereas overexpression of PIAS improved insulin sensitivity and visceral adipose tissue inflammation." (PMID 31906225, 2019).
renal clear cell carcinoma (1 paper, 2020). "SENP8 and PIAS1 play protective roles in renal clear cell carcinoma." (PMID 33123273, 2020).
Rett syndrome (1 paper, 2021). A severe neurodevelopmental disorder affecting the central nervous system.
small cell lung carcinoma (1 paper, 2015). Small cell lung cancer (SCLC) is a highly aggressive malignant neoplasm, accounting for 10-15% of lung cancer cases, characterized byrapid growth, and early metastasis. "Moreover, we performed dual luciferase reporter assay and Western blot on 6 targeted genes (FZD8, ITGA10, ITPKB, LRP5, PIAS1 andRUNX1) in small cell lung carcinoma cell line NCI-H82." (PMID 26642205, 2015).
type 2 diabetes mellitus (1 paper, 2021). A type of diabetes mellitus that is characterized by insulin resistance or desensitization and increased blood glucose levels. "In relation to our finding, several previous studies have highlighted the role of PIAS1 in diabetes mellitus or neurological diseases." (PMID 34857740, 2021). "We found that PIAS1 was notably downregulated in diabetes mellitus." (PMID 34857740, 2021). "Notably, it has been revealed that the critical role of PIAS1 exerted important functions in controlling insulin sensitivity and thus might be potential for treatment of type 2 diabetes mellitus." (PMID 34857740, 2021). "Notably, it has been revealed that PIAS1 exerted important functions in controlling insulin sensitivity and thus might be potential therapeutic target for treatment of type 2 diabetes mellitus." (PMID 34857740, 2021). "In order to explore whether PIAS1 plays a role in DPN, we first selected db/db mice and ob/ob mice to establish spontaneous diabetes mellitus model, and used WT C57BL/6 mice as NCs." (PMID 34857740, 2021).
ZIKV infection (1 paper, 2020). "Interestingly, a CRISPR/Cas9 screening revealed that PIAS1-depleted cells are more sensitive to ZIKV infection-dependent lethality." (PMID 31936331, 2020).
cancer (28 papers, 2010 to 2025). A tumor composed of atypical neoplastic, often pleomorphic cells that invade other tissues. "Sumoylation of AKT by PIAS1 causes its activation and deletion of the target K decreases the tumorigenic capacity of the E17K cancer-associated mutation." (PMID 35887358, 2022). "PIAS1 regulates PML in NSCL cancer, and it has been implicated in As2O3-mediated degradation of PML-RARα in APL." (PMID 23730625, 2013). "However, within PIAS1-expressing cells, we observed significant reduction in PIAS1 expression across almost all cancer-associated cell types compared to their normal counterparts (Wilcoxon rank-sum test, adjusted p < 0.0001)." (PMID 40941002, 2025). "Based on a previous study of Pias1-/- cells that employed microarray analysis, PIAS1 was also identified as a novel negative regulator of NF-κB that is associated with immunity and homeostasis in a number of human illnesses, such as chronic inflammatory diseases and cancer." (PMID 33759814, 2021). "In cancer, PIAS1 is involved in critical processes such as proliferation, apoptosis, DNA repair, and immune regulation." (PMID 40941002, 2025). "By studying individual cells from tumors, we saw that PIAS1 was often found in immune and support cells and seemed to help these cells fight cancer." (PMID 40941002, 2025). "We next compared the expression of immune checkpoint molecules between PIAS1+ and PIAS1-cells across tumor-infiltrating T cells, cancer cells, CAFs, and TAMs." (PMID 40941002, 2025). "This integrated dataset, containing both cancer-derived and normal TME cells, serves as a foundation for further investigating PIAS1-associated transcriptional changes within specific stromal populations." (PMID 40941002, 2025). "PIAS1 is a protein that helps control how cells behave, including how they respond to signals that can lead to cancer." (PMID 40941002, 2025). "PIAS1 and TIF1gamma promote the SnoN SUMOylation and suppression of epithelial mesenchymal transition cancers cells, but the regulation of EMT is still unclear." (PMID 38590645, 2024). "The results showed that they exhibited amplification patterns in most cancer types, and PIAS1 had the highest amplification pattern in UCES." (PMID 38528630, 2024). "In various cancer cells, PIAS1 enhances the transcriptional function of the Smad2/Smad4 protein complex." (PMID 38590645, 2024). "Our results showed that PIAS1 was significantly downregulated in ten cancer types and significantly upregulated in seven cancer types." (PMID 38528630, 2024). "In B-cell lymphoma, PIAS1 has been reported as a mediator in lymphomagenesis through SUMOylation of MYC, a proto-oncogene transcription factor associated with several cancers." (PMID 32047143, 2020). "It has been shown that PIAS1 modulates activation of Smad2/4 complex and further promotes Smad2/4 mediated proliferation inhibition observed in some cancer cells." (PMID 27553600, 2016). "Collectively, our data suggest that PIAS1 acts in a SUMO E3 ligase-dependent manner to suppress the ability of TGFβ to promote an aggressive invasive behavior in MDA-MB-231 cancer cell-derived organoids." (PMID 25594015, 2014). "Collectively, our findings reveal that the SUMO E3 ligase PIAS1 regulates TGFβ-induced cancer cell invasion and metastasis." (PMID 25594015, 2014). "To further extend our knowledge on PIAS1 and to evaluate if PIAS1 targeting can improve current cancer therapies, we performed a detailed analysis of PIAS1 expression and function in PCa." (PMID 25474038, 2014). "So far, we were able to demonstrate increased PIAS1 levels in docetaxel treated patients and in docetaxel resistant cell lines and proved that PIAS1 expression is crucial for cancer cell survival." (PMID 25474038, 2014). "As EMT is critical for proper development and in the progression of cancer, it will be important in future studies to identify the role of PIAS1 and sumoylated SnoN in these biological processes." (PMID 21103059, 2010).
cancer (continued). "However, when comparing PIAS1-positive cells, expression levels were significantly reduced in cancer cells, CAFs, TAMs, T cells, and endothelial cells within the TME." (PMID 40941002, 2025). "Overall, PIAS1 appears to play an important role in helping the body’s own cells resist cancer and could be a useful target for future treatments." (PMID 40941002, 2025). "To determine whether PIAS1 expression alters intercellular communication, we analyzed ligand–receptor interactions between PIAS1+ or PIAS1-CAFs, TAMs, and T cells and cancer cells using CellChat." (PMID 40941002, 2025). "Incoming signals from cancer cells to PIAS1+ CAFs were subtly altered, including integrin and laminin-mediated adhesion pathways (e.g., FN1–ITGAV_ITGB1, FN1–ITGA5_ITGB1, LAMB3–CD44 and LAMC2–CD44), which support basement membrane integrity rather than invasion." (PMID 40941002, 2025). "Previous sequencing data have indicated aberrant expression of hsa_circ_0007088 (derived from the PIAS1 gene, circPIAS1) in various cancers, but its regulatory role in HCC remains unclear." (PMID 38802795, 2024). "The most frequently reported PIAS family member in cancer development are PIAS1 and PIAS3." (PMID 38590645, 2024). "Most frequently reported PIAS family members in cancer development are PIAS1 and PIAS3." (PMID 38590645, 2024). "In general, PIAS1 is also involved in tumorigenesis through the regulation of the alternative lengthening of telomeres (ALT) pathway, causing its activation and maintenance of telomere length, essential for the development and maintenance of cancer." (PMID 35887358, 2022). "In addition to its regulatory role in PML/PML-RARα oncogenic signaling, PIAS1 has been shown to be involved in the cancer therapeutic mechanism of arsenic trioxide (ATO)." (PMID 32047143, 2020). "Altogether, these reports suggest that PIAS1 could promote cancer cell growth and progression by regulating the SUMOylation level on a pool of different substrates." (PMID 32047143, 2020). "In this study, we identify a novel function for PIAS1 in cancer metastasis." (PMID 25594015, 2014). "We conclude that PIAS1 is a common partner for two cancer-related nuclear factors, c-Myb and FLASH." (PMID 21338522, 2011). "In this study, we analyzed the expression of PIAS family genes (PIAS1, PIAS2, PIAS3, and PIAS4) in 33 different types of cancer." (PMID 38528630, 2024). "In epithelial cells, PIAS1-SnoN SUMOylation inhibits TGF-β-induced EMT, which suggests the fundamental role of SnoN-SUMOylation in cancer progression." (PMID 38590645, 2024). "An overexpression of PIAS1 and MYC was observed in stimulated B cells, substantial subset of prime B-cell lymphomas, and other cancer types." (PMID 38590645, 2024). "These three genes belong to enriched pathways associated with senescence/aging (PTEN belongs to pathways in cancer, PI3K-Akt signaling pathway; PIAS1 and DNMAT3A belong to transcription, DNA-templated, regulation of transcription)." (PMID 30835716, 2019). "Altogether, these data point to the importance of investigating the correlation between PIAS1, TIF1γ and SnoN in suppressing TGFβ-induced EMT and cancer invasiveness." (PMID 30096838, 2018). "PIAS1 suppresses TGFβ-dependent activation of the matrix metalloproteinase MMP2 and the invasiveness of breast MDA-MB-231 cancer cells." (PMID 25594015, 2014). "In PIAS1+ T cells, CD99–CD99 emerged as the dominant upregulated outgoing signal to cancer cells." (PMID 40941002, 2025). "A recent pan-cancer analysis across 33 cancer types noted tissue-specific variability in PIAS1 expression, but did not specifically examine OSCC." (PMID 40941002, 2025). "Strikingly, SS was the most sensitive subtype of cancer to knocking down UBE2I (UBC9), SUMO2 (the most widely expressed SUMO in humans), PIAS1, SAE1 and UBA2 (SAE2), molecules encompassing the entire SUMOylation process and pointing to a selective dependency of SS on this PTM." (PMID 38883782, 2024).
cancer (continued). "However, contrary to PIAS1 and PIAS3, PIAS4 favors the survival of cancer cells, promoting the overexpression and stability of lysine demethylase 5B (KDM5B) in hypoxia through its sumoylation, thus provoking the inhibition of CDKN1A (P21) transcription." (PMID 35887358, 2022). "Whilst other studies of PIAS1 suggest an important biological role in cancer, this study shows that PIAS1 has no influence on reducing the cytotoxic effects of Cisplatin or cell recovery after DNA damage induced by irradiation." (PMID 31639157, 2019). "Summed-up, the in vitro data presented here do not support the role of PIAS1 as a therapeutic target in UC cancer or as biomarker as previously shown in different entities." (PMID 31639157, 2019). "In contrast to other cancer types PIAS1 protein expression is not significantly different in malignant areas of UC specimens compared to non-malignant tissue." (PMID 31639157, 2019). "Cancer cell type specific co-regulators included SP1, NCOA1, NCOA2, and PIAS1." (PMID 28117763, 2017). "Hence, our study strengthens the link between two cancer-related nuclear factors, c-Myb and FLASH, through their common interaction with PIAS1." (PMID 21338522, 2011). "PIAS1 may function as an E3 ligase for ligand-activated nuclear receptor peroxisome proliferator-activated receptor (PPAR) gamma, which is modified by SUMO-1 and is a potential target for apoptosis-induction therapy in cancer cells." (PMID 33759814, 2021). "Thus, PIAS1 may serve as a general biomarker in cancer with positive or negative relationship to survival dependent on cancer types." (PMID 28493978, 2017). "The inhibition of TGF-β-induced EMT through SUMO E3 ligase PIAS1 and SnoN SUMOylation raises a question whether or not low level and subcellular localization of PIAS1 enhanced TGF-β-induced EMT and cancer metastasis." (PMID 38590645, 2024). "Furthermore, it is worth noting that modulation of cellular CP2b concentration, but not that of PIAS1, also affected the GI50 values of ACP52C in cancer cells." (PMID 37845006, 2023).
tumor (22 papers, 2010 to 2025). "Kaplan–Meier analysis revealed that patients with high stromal PIAS1 expression were associated with significantly improved overall survival (p = 0.0027), suggesting a tumor-suppressive role of PIAS1 in the OSCC TME." (PMID 40941002, 2025). "High PIAS1 expression within individual cells is associated with tumor-suppressive transcriptional programs across the OSCC TME." (PMID 40941002, 2025). "Single-cell analysis across three independent OSCC cohorts revealed that PIAS1+ stromal and immune cells exhibit cell-type-specific transcriptional programs associated with tumor suppression." (PMID 40941002, 2025). "Future studies employing genetic knockdown or knockout models of PIAS1 in CAFs, tumor-associated macrophages TAMs, or immune cell co-culture systems will be essential to substantiate the mechanistic hypotheses proposed here." (PMID 40941002, 2025). "The consistent association between stromal PIAS1 expression and favorable biological features, including tumor cell death, pro-inflammatory signaling, and reduced immune checkpoint expression, supports its role as a critical orchestrator of an immune-active microenvironment." (PMID 40941002, 2025). "Furthermore, PIAS1 knockdown experiments revealed an increased expression of tumor suppressor p21 and declined expression of anti-apoptotic protein Mcl1, which caused diminished cell proliferation and tumor growth in vitro and in vivo." (PMID 25474038, 2014). "This reduction in expression within PIAS1-positive cells suggests a potential functional silencing or repression of PIAS1 activity within the tumor milieu." (PMID 40941002, 2025). "CellChat-based ligand–receptor modeling showed that PIAS1 reprograms intercellular communications toward anti-tumor signaling." (PMID 40941002, 2025). "PIAS1+ T cells exhibited significant reduction in tumor cell viability and activation of cell death pathways." (PMID 40941002, 2025). "In TAMs, SPP1–CD44 and related integrin signals, key mediators of M2 polarization, were suppressed in PIAS1+ cells, while tumor-derived MIF signals promoting M1-polarizing were enhanced." (PMID 40941002, 2025). "In TAMs, PIAS1 expression correlated with tumor cell death and inflammatory functions, while functions associated with immune cell death, tumor proliferation, invasion, and metastasis were among the most strongly inhibited." (PMID 40941002, 2025). "PIAS1 modulates cell–cell interactions and transcriptional states across CAFs, TAMs, and T cells, collectively promoting a tumor-suppressive TME." (PMID 40941002, 2025). "PIAS1-positive CAFs, TAMs, and T cells exhibited activation of apoptotic and tumor-suppressive pathways, while PIAS1-negative counterparts showed enrichment of immunosuppressive signaling and immune checkpoint expression." (PMID 40941002, 2025). "In CAFs, PIAS1+ cells showed downregulation of immunosuppressives MIF–CD74_CD44 signaling and upregulation of tumor-suppressive CD99–CD99 interactions associated with immune activation." (PMID 40941002, 2025). "In PIAS1+ CAFs, ligand–receptor interactions revealed a shift toward a less tumor-promoting phenotype." (PMID 40941002, 2025). "IPA indicated that PIAS1+ CAFs were enriched in pathways involved in tumor necrosis and apoptosis, along with suppression of functions related to tumor growth." (PMID 40941002, 2025). "For example, downregulation of PIAS1 inhibits the differentiation of tumor cells in liver cancer, and it also serves as a biomarker to distinguish colon cancer from adenomas." (PMID 38528630, 2024). "This suggests that PIAS1-mediated sumoylation of RUNX plays a role in regulating the tumor suppressor activity of these proteins." (PMID 35887358, 2022). "The tumor suppressor promyelocytic leukemia protein (PML) is modified by SUMOylation by interacting with PIAS1, which promoted its ubiquitin-mediated degradation in acute promyelocytic leukemia and thus attenuated its tumor suppressor functions." (PMID 33273928, 2020).